ABCD2 (ATP binding cassette subfamily D member 2)
Diseases named in the same sentence as ABCD2 in open-access papers (continued):
Sharing a sentence is not in itself a finding about the gene and the disease.
ischemic stroke (3 papers, 2014 to 2022). A stroke disorder caused by obstruction of blood flow to the brain, due to thrombotic (local blood clot formation) or embolic (due to a blood clot or other material traveling from another site) event. "We analyzed if the risk of ipsilateral ischemic stroke differed between various cut-offs for ABCD2 and ABCD3 scores." (PMID 25433667, 2014). "However, hypertension history and ABCD2 ≥ 4 were independently related to recurrent ischaemic stroke risk at 90 days (HR 2.098, 95% CI 1.232–3.573, p = 0.006; HR 1.836, 95% CI 1.129–2.985, p = 0.014)." (PMID 30718523, 2019). "We analyzed the risk of recurrent ipsilateral ischemic stroke before carotid endarterectomy based on each parameter of the ABCD2 and ABCD3 scores separately, and for total ABCD2 and ABCD3 scores." (PMID 25433667, 2014). "The aim of this study is to analyze the ability of ABCD2 and ABCD3 scores to predict ipsilateral ischemic stroke among patients with symptomatic 50-99% carotid stenosis." (PMID 25433667, 2014). "The aim of this study is to analyze the ability of the ABCD2 and ABCD3 scores to predict recurrent ipsilateral ischemic stroke among patients with symptomatic 50-99% carotid stenosis." (PMID 25433667, 2014). "The evaluated ABCD2-, ABCD3-score and SPI-II, which all stratify the risk for ischemic stroke after TIA, were not predictive for ipsilateral vascular pathologies or the need for invasive treatment in our study." (PMID 34980008, 2022).
ovarian carcinoma (3 papers, 2014 to 2025). A malignant neoplasm originating from the surface ovarian epithelium. "Functional study found that knocking down ABCD2 in vitro led to increased apoptosis in ovarian cancer cell line SKOV3 after cisplatin treatment." (PMID 24739237, 2014). "We found that reduction of ABCD2 expression by siRNA knockdown led to an increase in apoptotic activity after treatment with cisplatin, suggesting that ABCD2 plays a role in cellular sensitivity to the platinums in ovarian cancers." (PMID 24739237, 2014). "To gain insight into the function of ABCD2 in cancer, we performed gene knockdown experiments in an ovarian cancer cell line, SKOV-3." (PMID 24739237, 2014).
brain inflammation (2 papers, 2016 to 2025).
breast carcinoma (2 papers, 2015 to 2019).
Hepatic steatosis (2 papers, 2025). Steatosis is a term used to denote lipid accumulation within hepatocytes. "ABCD2 knockout mice, a mouse model of X-ALD patients, developed hepatic steatosis when fed an erucic acid (C22:1) enriched diet." (PMID 40943222, 2025).
acne (1 paper, 2014). An inflammatory process of the sebaceous glands which is characterized by comedones, nodules, papules and/or pustules on the skin. "In treated acne patients, ABCD2 mRNA levels were comparable to pre-treatment levels in monocytes and lymphocytes." (PMID 25079382, 2014). "To test the efficacy of retinoids in vivo, we analyzed ABCD2 mRNA levels in blood cells isolated from acne patients receiving 13-cis-retinoic acid therapy." (PMID 25079382, 2014). "However, in human primary monocytes isolated from acne patients treated with 13CRA, ABCD2 mRNA levels were unchanged when compared with pretreatment levels or healthy controls." (PMID 25079382, 2014).
atherosclerosis (1 paper, 2022). A disease characterized by the build-up of fatty material and calcium deposition in the arterial wall resulting in partial or complete occlusion of the arterial lumen. "ABCB5, a gene previously not studied in the context of atherosclerosis, emerged as one of the top upregulated in plaques from both high-risk CAR and ABCD2 patients." (PMID 35494231, 2022). "ABCB5, previously not described in the context of atherosclerosis, was one of the top genes identified by both high CAR and ABCD2 risk scores, localized to macrophages, IPH, and neovessels in plaques from symptomatic patients." (PMID 35494231, 2022).
Cerebral ischemia (1 paper, 2010). Restriction of arterial blood supply to the brain associated with insufficient oxygenation to support the metabolic requirements of the tissue. "Notably, patients with a moderate or high ABCD2 score were significantly more likely to show DWI signal intensity changes suggestive of cerebral ischemia than patients with a low ABCD2 score." (PMID 20565966, 2010).
cognitive decline (1 paper, 2020). "Finally, the ABCD2, which also loads heavily on vascular risk factors, varied across neurological event type and was associated with cognitive decline, independently of event type." (PMID 32373041, 2020).
depression (1 paper, 2020). "The addition of depression in the model scarcely affected coefficients from those presented and was not included in any of the ABCD2 models." (PMID 32373041, 2020).
epilepsy (1 paper, 2013). A brain disorder characterized by episodes of abnormally increased neuronal discharge resulting in transient episodes of sensory or motor neurological dysfunction, or psychic dysfunction. "Additionally, the effect of SAHA was investigated in hippocampal slice cultures from patients suffering from drug-resistant epilepsy that were scheduled for hippocampal resection, where it upregulated the ABCD2 expression." (PMID 23923017, 2013).
leukemia (1 paper, 2025). A malignant (clonal) hematologic disorder, involving hematopoietic stem cells and characterized by the presence of primitive or atypical myeloid or lymphoid cells in the bone marrow and the blood. "Next, we knocked down ABCD2 in two human leukemia cell lines, MV4-11 and MOLM13." (PMID 38913865, 2025). "Moreover, the very long chain fatty acid transporter ATP-binding cassette subfamily D member 2 (ABCD2) is a key factor that promotes AML development, and deletion of ABCD2 damages clonogenic ability, inhibits proliferation, and promotes apoptosis of human leukemia cells." (PMID 38913865, 2025).
osteoarthritis (1 paper, 2021). A noninflammatory degenerative joint disease occurring chiefly in older persons, characterized by degeneration of the articular cartilage, hypertrophy of bone at the margins and changes in the synovial membrane. "Recent study also elicited that peroxisome ATP binding cassette, subfamily D, member 2 (ABCD2), in osteoarthritis chondrocytes can affect miR-141 expression, downregulate the expression of acyl-CoA synthetase 4 (ACSL4), and thus induce the accumulation of very long chain fatty acids (VLCFAs)." (PMID 34659401, 2021).
osteoporosis (1 paper, 2023). A condition of reduced bone mass, with decreased cortical thickness and a decrease in the number and size of the trabeculae of cancellous bone (but normal chemical composition), resulting in increased fracture incidence. "Five genes remained after the LASSO feature selection, and the formula for the osteoporosis risk score (ORS) was established as follows: ORS = 33.991 - 2.272 * ABCD2 - 6.201* RORA + 2.237 * ITK - 1.100 * CAMK4 + 0.466 * RASGRP1." (PMID 37051201, 2023).
stenosis (1 paper, 2022). "Moreover, we speculated that the combination of miR‐200b‐3p, ABCD2 score, and carotid stenosis degree by ultrasound may propose as an efficient predictive strategy for the prediction of CI in TIA patients." (PMID 35261213, 2022).
Zellweger syndrome (1 paper, 2014).
infection (19 papers, 2013 to 2024). The state of being infected such as from the introduction of a foreign agent such as serum, vaccine, antigenic substance or organism.
cancer (8 papers, 2011 to 2025). A tumor composed of atypical neoplastic, often pleomorphic cells that invade other tissues. "ABCD2 is part of the peroxisomal transporter family and has been implicated in the regulation of lipid metabolism, which is critical for energy homeostasis and cellular proliferation in cancer." (PMID 39931063, 2025). "The observed upregulation of metabolic genes, such as ABCD2 and FBP1, following VD-LP treatment, suggests that the liposomal formulation may influence key pathways in cancer metabolism." (PMID 39931063, 2025).
tumor (4 papers, 2015 to 2025). "Enhanced ABCD2 expression may reflect a shift in the metabolic state of tumor cells toward pathways less favorable for tumor progression, potentially through altered fatty acid oxidation or lipid biosynthesis." (PMID 39931063, 2025).
neurological disease (1 paper, 2012). "The significantly-populated signaling pathway “neurological disease” comprised both protein kinase, AMP-activated, alpha 2 catalytic subunit (Prkaa2) and ATP-binding cassette, subfamily D, member 2 (Abcd2)." (PMID 22934110, 2012).
ABCD2 also shares sentences with these, for which no sentence is quoted: bacterial infection (3 papers); hyperlipidemia (2); Hypertension (2); adrenoleukodystrophy (1); Autoimmunity (1); bacteremia (1); carotid atherosclerosis (1); cerebral infarction (1); colon cancer (1); cyst (1); dyslipidemia (1); gastric cancer (1); genetic disorder (1); head and neck squamous cell carcinoma (1); infarction (1); Insulin resistance (1); melanoma (1); Mitchell syndrome (1); myeloproliferative neoplasm (1); non-small cell lung carcinoma (1); Nystagmus (1); pancreatic cancer (1); peroxisomal biogenesis disorders (1); prostate carcinoma (1); renal cell carcinoma (1); tuberculosis (1); Vertigo (1); vestibular neuritis (1).